PRMT5 (protein arginine methyltransferase 5)
Diseases named in the same sentence as PRMT5 in open-access papers (continued):
Sharing a sentence is not in itself a finding about the gene and the disease.
cancer (continued). "Here we describe broad anti-proliferative activity of potent, selective, reversible inhibitors of protein arginine methyltransferase 5 (PRMT5) including GSK3326595 in human cancer cell lines representing both hematologic and solid malignancies." (PMID 29946150, 2018). "The identification of this novel PRMT5 inhibitor T1551 and its inhibitory mechanism study will be helpful for the development of PRMT5-targeting cancer treatment." (PMID 29545752, 2018). "Since PRMT5 is also widely involved in the pathologic progress of cancer metastasis, we tested if PRMT5 was a target of SHARPIN." (PMID 28903384, 2017). "PRMT5 has been shown to be upregulated in a number of different cancers and plays an essential role in growth of various cancer cells." (PMID 28806746, 2017). "Overexpression of PRMT5 promoted cancer progression, while shRNA knockdown showed an opposite effect." (PMID 28591716, 2017). "The ChIP-qPCR profile of all these histone PTMs supports the idea that SHARPIN is essential for PRMT5 in maintaining unique H3 arginine methylation (H3R2me1), which surrounds the promoter regions of cancer metastasis-related genes." (PMID 28903384, 2017). "Protein arginine methyltransferase-5 (PRMT5) plays an important role in cancer progression by repressing the expression of key tumor suppressor genes via the methylation of transcriptional factors and chromatin-associated proteins." (PMID 28107179, 2017). "In order to test this possibility, we examined the effect of PRMT5 on various characteristics of cancer cells including cell proliferation, anchorage-independent growth, and cell migration." (PMID 28591716, 2017). "These inhibitors selectively inhibited PRMT5 activity as well as growth of some cancer cells or tumor xenografts." (PMID 28806746, 2017). "Together, our results in conjunction with others imply that elevated PRMT5 expression within cancer stem cells offers a therapeutic window for drug treatment." (PMID 29262329, 2017). "Recent studies have shown that PRMT5 is overexpressed in a number of cancer types including ovarian, lung, colon, gastric and bladder cancer and is associated with poor clinical outcome." (PMID 28107179, 2017). "The role of PRMT5 in cancer, particularly in regulating the expression of key tumor suppressor genes, has been extensively studied." (PMID 28107179, 2017). "Strikingly, using L-Calc (Stem Cell Technologies) to calculate stem cell frequency, we show that depletion of PRMT5 reduced cancer stem cell numbers from 1:187,878 to 1:1,042,530, a 5.5-fold reduction." (PMID 29262329, 2017). "Overexpression of PRMT5 promoted cancer progression through increased activation of NF-κB, cell growth, anchorage-independent growth and cell migration in both PDAC and CRC." (PMID 28591716, 2017). "Our results shed light on the involvement of ROK/MP enzyme pair in the phosphorylation/dephosphorylation of the protein arginine methyltransferase 5 (PRMT5) via regulating arginine methylation of histones thereby affecting signaling for cancer formation." (PMID 28074910, 2017). "The protein expression of PRMT5 showed an increase in ~75% of the investigated cancer tissues comparing to the healthy controls." (PMID 28074910, 2017). "Taken together, our data are highly suggestive that depletion of PRMT5 in established carcinomas reduces tumor propagation by restricting the number of BCSCs." (PMID 29262329, 2017). "Although these results suggest that PRMT5 is required to sustain the growth of an established carcinoma, we wanted to determine if this was through the maintenance of the BCSC population." (PMID 29262329, 2017). "WDR77 and PRMT5 are ubiquitously re-expressed in lung hyperplasia and cancer and conversely, GLIPR1 expression is significantly down-regulated during lung tumorigenesis." (PMID 26988096, 2016). "PRMT5 over‐expression in a variety of cancers is thought to silence tumour suppressor genes (TSGs) such as ST7 (suppression of tumorigenicity 7) and genes encoding RB family proteins." (PMID 25475372, 2015).
cancer (continued). "As MYCN is an oncogenic driver in a wide variety of cancers, our findings highlight the importance of developing PRMT5 small molecule inhibitors for cancer therapeutics targeting MYCN; currently no specific inhibitors are available." (PMID 25475372, 2015). "Statistical analysis revealed that expression levels of PRMT5 significantly increased in cancer tissues compared to the corresponding NATs." (PMID 26078354, 2015). "Statistical analysis revealed that PRMT5 level significantly increased in cancer tissues compared with the corresponding NATs." (PMID 26541651, 2015). "PRMT5 emerges as an important regulator of multiple cellular processes and is expressed aberrantly in different types of cancer." (PMID 26541651, 2015). "Another protein, protein-arginine methyltransferase 5 (PRMT5), is overexpressed in many cancers and promotes tumorigenesis by stimulating NF-κB." (PMID 24885472, 2014). "There is no direct evidence for dysregulation of other PRMTs, such as PRMT2, PRMT4 and PRMT5 in lung tumorigenesis, although these molecules participate in the pathogenesis of other types of human cancer." (PMID 23202904, 2012). "Abnormal expression of PRMT5 has been shown to contribute to drug resistance in cancer." (PMID 41513606, 2026). "Thus, combination cancer therapy involving two or more treatments, like a PRMT5 inhibitor combined with chemotherapy as used in this study, targets PDAC cells more effectively and improves treatment outcomes." (PMID 40723820, 2025). "PRMT5 is upregulated and involved in the progression of various cancers." (PMID 39668577, 2025). "Notably, in line with the CCLE data, we observed that OC, as a whole, had the second-highest expression of PRMT5 compared with all other cancer types." (PMID 40091834, 2025). "Recent studies have identified that the absence of MTAP in cancer cells renders them more susceptible to PRMT5 and MAT2A depletion." (PMID 40430461, 2025). "We reasoned that compounds that preferentially inhibit PRMT5 in the presence of MTA might constitute an attractive modality to treat MTAP-deleted cancers with less adverse effects on normal tissues." (PMID 40377999, 2025). "Recently, PRMT5 has become an intriguing treatment option for treating cancer." (PMID 39781264, 2025). "These compounds provided a proofof concept that MTAP-deleted cancers could be targetedwith MTA-cooperative PRMT5 inhibitors." (PMID 39919252, 2025). "Furthermore, PRMT5 is highly expressed in many cancers and broadly promotes oncogenesis, thus providing a rationale for clinical evaluation of PRMT5 inhibition." (PMID 40377999, 2025). "Consequently, MTAP deleted cancers are particularly vulnerable to further inhibition with second-generation PRMT5 inhibitors that can selectively target the PRMT5:MTA complex leading to a synthetic lethal relationship." (PMID 40823091, 2025).
cancer (continued). "Here, we report that TLR3 in cancer cells undergoes nuclear translocation under chemotherapeutic stress and acts as an oncogenic protein to recruit arginine methyltransferase PRMT5 to promote dimethylation and multimerization of c-Myc, consequently facilitating cancer metastasis and chemoresistance." (PMID 40675966, 2025). "Moreover, PRMT5 is overexpressed in many human cancers and has been increasingly recognized as a promising anticancer target." (PMID 40723820, 2025). "PRMT5 catalyses the majority of symmetric dimethylation (SDMA) in mammalian cells, and its association with cancer progression in both solid and haematological disease has prompted the rapid development of small molecule inhibitors that are now in clinical trials." (PMID 39695328, 2025). "•Methionine restriction induces hypersensitivity to Prmt5 inhibitors in cancer cells." (PMID 39862967, 2025). "The durable PD hold by TNG462 observed in vivo was supported by an in vitro studydemonstrating that TNG462 conferred strong thermostabilityto cellular PRMT5 even after compound had been removed for 72 h ina washout study using the LN18 MTAP-null cancer cell line." (PMID 40035511, 2025). "We next asked whether these nutrient-induced effects on Prmt5 present a major pathway that links cell proliferation defects in homocysteine medium to methionine-dependence of cancer." (PMID 39862967, 2025). "This study introduces a broadly applicable method for directed DNA-encoded library screening toward a desired mechanistic outcome and highlights MTA-selective PRMT5 inhibition as an attractive therapeutic strategy with a potentially broad therapeutic index in patients with MTAP-deleted cancers." (PMID 40377999, 2025). "This suggests that ZMYND11 could serve as a valuable biomarker for guiding clinical diagnostics and therapy in cancer, particularly when considering the use of PRMT5 inhibitors." (PMID 39341825, 2024). "Moreover, we have also demonstrated that FXR1 demethylation through inhibition of PRMT5 affected the protein stability and reduced the cancer cell proliferation." (PMID 38709899, 2024). "Thus, interference with PRMT5 activity has become a feasible and effective strategy for promoting cancer vulnerability in NDRG2low ATL." (PMID 38474089, 2024). "The subcellular localization of PRMT5 significantly affects its function in cancer cells." (PMID 38791992, 2024). "Preclinical studies have shown that inhibition of PRMT5 activity suppresses tumor cell proliferation in vitro and in animal models slows tumor growth and prolongs survival, suggesting that PRMT5 provides a target for cancer therapy." (PMID 39068290, 2024). "Notably, in various tumors including lung, breast, stomach, and liver etc., PRMT5 is overexpressed, which underscores its implication in cancer pathology." (PMID 39614393, 2024). "Furthermore, PRMT5 has been shown to be upregulated in several cancers and genetic or pharmacological downmodulation of its activity promotes cell death of cancer cells." (PMID 38730267, 2024). "Because the combination with the downregulation of tumour suppressors and genes involved in cell proliferation is a candidate for synthetic lethality, cytoplasmic PRMT5/MEP50 may be a therapeutic target in NDRG2low cancers." (PMID 38474089, 2024). "Furthermore, the expression of AKT and NEMO proteins was decreased in those ATL cells in a dose-dependent manner, thus indicating that PRMT5/MEP50 inhibition can be a promising therapeutic target for cancer vulnerability in NDRG2low ATL cells." (PMID 38474089, 2024). "Thus, PRMT5 appears to play dual roles in cell viability in a context-dependent fashion, being pro-proliferation in cancer and stem cells but pro-cell death under ischemic conditions." (PMID 38372724, 2024).
cancer (continued). "We hypothesized that the targeted inhibition of PRMT5 in NDRG2low ATL and solid cancer cells would specifically induce anti-cancer effects as synthetic lethality through the inhibition of cytoplasmic PRMT5/HSP90 activity." (PMID 38474089, 2024). "SRSF1, acting as a direct target of PRMT5, plays a crucial role in promoting cancer in AML." (PMID 38302461, 2024). "Future studies should aim to include clinical samples collected before and after PRMT5 inhibitor treatment to rigorously test this hypothesis in well-defined cohorts of cancer patients." (PMID 39341825, 2024). "Given the critical role for PRMT5 to promote ISGs and cytokine transcription in the context of RS, a condition common in cancer, the inhibition of this enzyme may affect the TME." (PMID 38838142, 2024). "Moreover, PRMT5 was also reported to increase the expression of transient receptor potential cation channel, subfamily V, member 6 and then subsequently influence cancer cell proliferation, apoptosis and autophagy." (PMID 39678513, 2024). "Several PRMT5 inhibitors are currently under clinical trial studies for cancer therapy." (PMID 38791992, 2024). "Furthermore, we demonstrate that tumors with low ZMYND11 expression exhibit enhanced sensitive to inhibitors of the type II arginine methyltransferase PRMT5, highlighting a potential therapeutic avenue for targeting cancers with ZMYND11 dysregulation." (PMID 39341825, 2024). "Consequently, the formation of PRMT5-MTA complexes sensitizes MTAP-deleted cancer cells to enable further PRMT5 inhibition." (PMID 38610930, 2024). "Among them, PRMT5 has been identified as an oncogenic factor in various cancers." (PMID 39594744, 2024). "Preclinical studies suggest PRMT5 regulation of DDR pathways may be a therapeutic opportunity, and PRMT5 inhibition may increase the sensitivity of cancer cells to PARP inhibition." (PMID 39201539, 2024). "PRMT5 has emerged as a synthetically lethal drug target for the treatment of MTAP-deleted cancers." (PMID 39337530, 2024). "Additionally, PRMT5 has emerged as a key mediator of AKT’s oncogenic activity through methylation, promoting tumor cell metastasis, and targeting PRMT5 shows promise for cancer therapy." (PMID 39635438, 2024). "PRMT5 is a major disymmetric arginine methyltransferase in mammalian cells and might be a vital therapeutic target molecule for cancer treatment." (PMID 39255317, 2024). "Furthermore, loss-of-function of PRMT5 inhibited FXR1 methylation both in vivo and in vitro, affecting FXR1 protein stability, inhibiting RNA-binding activity and cancer cell growth and proliferation." (PMID 38709899, 2024). "Consequently, in MTAP−/− tumors the synthetic lethal inhibition of MAT2a ultimately converges on PRMT5 inhibition that reduces cancer growth and induces cell death." (PMID 38000655, 2024). "Similarly, PRMT5 influences gene expression, cell cycle control, and maintenance of cancer stem cells, contributing to tumor progression and poor prognosis." (PMID 39201539, 2024). "In cancer, PRMT5 protein was found to show different cellular localization between normal and tumor tissues and between tumor types, suggesting that its compartment-specific functions may regulate distinct molecular programs." (PMID 38372724, 2024). "Although their study did not focus on RB-deficient cancers, it provided important insights into the mechanism by which PRMT5 regulates cell cycle progression." (PMID 38480701, 2024). "Also, several studies have established PRMT5 as a reliable prognostic marker for cancers, including HCC." (PMID 38666828, 2024). "PRMT5 has oncogenic properties, and its level of expression is high in various cancers." (PMID 37458145, 2023). "Several PRMT5 inhibitors are now in early-stage clinical trials for different types of cancers." (PMID 37795443, 2023).
cancer (continued). "Moreover, we discovered that the expression of PRMT5 was significantly lower in cancer and was negatively correlated with the abundance of PD1+ CD8+ cells in 30 ccRCC patients by mIHC." (PMID 37781030, 2023). "In the past few years, PRMT5 has been proposed as a possible therapeutic target for some cancers." (PMID 36982984, 2023). "The involvement of PRMT5 has been verified in the epigenetic regulation of chromatin complexes following interaction with numerous proteins, including transcription factors, and their activities are dysregulated in various cancers." (PMID 38136401, 2023). "The potential impact of PRMT5 inhibition on MYC makes it an attractive target in various cancers." (PMID 38136401, 2023). "PRMT5 overexpression has been observed in several cancers (see Section 5.1)." (PMID 36980950, 2023). "Other PRMT5 inhibitors have been shown to induce apoptosis in several different cancer cell lines." (PMID 36819050, 2023). "PRMT5 has emerged as a major player in cellular transformation and cancer evolution." (PMID 37047013, 2023). "However, it has been found that a daily dose of >50 mg/kg is required to inhibit PRMT5‐mediated cancer growth in mice." (PMID 36946061, 2023). "Despite the findings in this study, additional investigation of PRMT inhibition remains warranted regarding, both the interplay between type I and type II PRMT (PRMT5) inhibition and the respective utility of targeting each individually for the treatment of cancer." (PMID 37237172, 2023). "Thus, PRMT5 has been actively studied as a cancer treatment target, and small molecule inhibitors of its enzymatic activity have already been developed." (PMID 37047013, 2023). "PRMT5 is an oncogene, overexpressed in several human cancers, and is related to poor prognosis." (PMID 36959798, 2023). "Recently, PRMT5 as an anti-cancer target has gained considerable interest." (PMID 36765032, 2023). "Therefore, PRMT5 inhibition would help recover the immune cycle and enable the immune system-mediated elimination of cancer cells." (PMID 36980950, 2023). "Here, we discuss the rationale and methods for targeting the MAT2A/PRMT5 axis for cancer therapy." (PMID 37795443, 2023). "PRMT5 loss impairs HR and enhances the toxicity of PARP inhibitors in other cancer types." (PMID 38201511, 2023). "So, it’s rational to expect that inhibiting PRMT5 may render cancer cells sensitive to ionizing radiation (IR) treatment." (PMID 36959798, 2023). "Identifying the major substrates of PRMT5 that are still methylated in MTAP-deleted cancers may be important to understanding what reactions PRMT inhibitors are acting on in these cancers." (PMID 38134182, 2023). "Many PRMT5 inhibitors have entered clinical trials for the treatment of multiple types of cancer." (PMID 38136401, 2023). "Whether these differences are due to cancer type, cell lines, or different PRMT5 inhibitors remains to be investigated in the future." (PMID 36765032, 2023). "Given that the PARP inhibitors niraparib and rucaparib are currently approved for the maintenance of HR proficient cancers, PRMT5 inhibition may represent a combination to expand the utility of PARP inhibition to earlier lines of therapy." (PMID 37596538, 2023). "Exploring PRMT5 as a potential therapeutic target for cancer treatment is an active area." (PMID 37461162, 2023). "PRMT5 overexpression is a recognized prognostic indicator of poor survival in several cancers." (PMID 37627211, 2023). "The pan-cancer analysis of PRMT5 mutations described in this report showed that not all mutations have an equal impact on cancer." (PMID 37047013, 2023). "Clinically, PRMT5 overexpression has been observed in a variety of cancers." (PMID 37400460, 2023). "However, in some cases, PRMT5 acts through H3R8me2s to upregulate specific genes in cancer, such as those related to eukaryotic initiation factor 4E, fibroblast growth factor receptor 3, and androgen receptor 51,52." (PMID 37928266, 2023).